CD4 (CD4 molecule)
Diseases named in the same sentence as CD4 in open-access papers (continued):
Sharing a sentence is not in itself a finding about the gene and the disease.
tumor (continued). "We next explored how OX40L-FP and MVA-Twist-TRICOM vaccine can enhance total and antigen-specific CD4+ and CD8+ T-cell responses in non-tumor-bearing Balb/c mice." (PMID 29207606, 2017). "CD4-positive (CD4 + CD25 + Foxp3+) regulatory T cells (Tregs) play an essential role in immunosuppression and self-tolerance of tumor antigens in patients with cancer or tolerance of microbial antigens in patients with chronic infection." (PMID 28545581, 2017). "Immunization was accompanied by induction of high anti-EGFRvIII antibody titers, M30-specific T cells, and infiltration of CD4+ and CD8+ T cells at the tumor site." (PMID 29164053, 2017). "Together, these results demonstrate that dual treatment leads to enhanced infiltration of CD4+ and CD8+ effector T cells, with elevated activation markers (elevated granzyme B, perforin and IFN-γ), as well as reduced Tregs in the tumour tissues." (PMID 28345650, 2017). "In this context, we observed a significant increase of TNF-α expressing CD4+ and CD8+ T-cells, indicating that these T-cells can directly induce SMC-mediated tumour cell death." (PMID 28198370, 2017). "The S-CTLA-4 mean score in the PTs was, in both stromal and tumor epithelial compartments, extensively correlated with other immunological markers previously analyzed by our group (CD3, CD4, CD8, CD45RO, CD20, PD-1, PD-L1), while T-CTLA-4 in PTs was not." (PMID 28707078, 2017). "We assume that the total density of cancer cells (C), active dendritic cells (D), CD4+ T cells (T1) and CD8+ T cells (T8) within the tumor remains constant in space and time:C+D+T1+T8=constant." (PMID 28542574, 2017). "This also suggests a pro-tumorigenic function of infiltrating CD4+ T cells in CRC patients, as accumulation of CD8+ T cells would have indicated a tumor-specific immune response as a protective function against cancer." (PMID 28603527, 2017). "IL-12 secreted by DCs promotes the induction of CD4+ Th1 cells and cytotoxic T lymphocytes (CTL) to suppress tumor growth." (PMID 28404904, 2017). "It has been shown that CD74 regulates the repertoire of antigens presented by MHCII and that this leads to primary engagement of CD4 and then CD8 components of the adaptive immune response, leading to tumor rejection." (PMID 27058619, 2017). "Using the MMTV-PyMT model, it was found that CD4+ T helper cells can induce alternative activation of TAMs and secretion of EGF, to directly promote tumor invasion and egress from the primary tumor as a result of IL4 activation." (PMID 28883015, 2017). "The ratio of peripheral CD4+ cells and CD8+ cells significantly increased at 2 weeks after tumor inoculation in group F (CD4+ (%), p = 0.0003; CD8+ (%), p = 0.0002) and group G (CD4+ (%), p = 0.007; CD8+ (%), p = 0.014) when compared with group H." (PMID 28864944, 2017). "The decrease in CD4 and Arg-1 in Cysltr1−/− mice could be explained by the finding that CD4+ Th2 cells can facilitate the expression of arginase-1 in murine macrophages, and arginase itself can promote tumor growth and the down-regulation of tumor cytotoxicity." (PMID 28410235, 2017). "Patients with late stage HNSCC (UICC stage III/IV) demonstrated a slightly increased CD4/CD8 ratio compared to early stage tumors in PBMC and tumor microenvironment (3.9 ± 3.7 vs. 2.5 ±1.9; 4.4 ± 6.6 vs. 2.7 ± 3.5, respectively)." (PMID 28574843, 2017). "A high degree of CD8+ and CD4+ T-cell infiltration in ESCC correlated with favorable clinical outcome, suggesting that tumor antigen-specific cellular immune response plays a role in the clinical course of the disease." (PMID 28404915, 2017). "Among the adaptive immune cells, both CD4+ T helper cells and CD8+ cytotoxic T cells are mostly considered to be significant players in inhibiting, impeding, and killing tumor cells." (PMID 28382040, 2017). "We found CD4+ and CD8+ T cells, B cells, macrophages, natural killer cells, dendritic cells and tumor cells in the fluids." (PMID 29163783, 2017).
tumor (continued). "In general, GITR crosslinking with agonistic antibodies enhances effector responses of the conventional CD4+ and CD8+ T cells both in the setting of chronic viral infections or tumor cell growth." (PMID 28638937, 2017). "PD-L1 expression in tumor cells was positively correlated with the numbers of CD3+, CD4+, CD8+, and FoxP3+ TILs (P = 0.027, P = 0.037, P = 0.003, and P = 0.006, respectively), but not with PD-1+ TILs or CD20+ TILs (P > 0.05)." (PMID 29029502, 2017). "Many studies proved the prognostic value of tumor-infiltrating lymphocytes of different subtypes, including CD3+, CD4+, CD8+, Treg cells." (PMID 28624781, 2017). "TGF-β is integral to the maintenance and generation of immunosuppressive Treg cells that inhibit the antitumor immune functions of tumor-specific CD8+ and CD4+ T cells by cell-cell contact and production of immunosuppressive cytokines such as IL-10 or TGF-β." (PMID 28002796, 2017). "Sublethally irradiated mice were reconstituted with ex vivo—expanded CD4+Ly5.1+ T cells, followed by the injection of MCA205 tumor cells." (PMID 28854279, 2017). "Immunohistochemistry analysis of paraffin embedded tumor sections showed more abundant CD3+ and CD4+ T cells infiltrating NXS2, than Neuro2a tumors, while B220+ B cells and myeloid cells (identified by staining for myeloperoxidase) were similarly represented." (PMID 29070883, 2017). "Some CD4+NKG2D+ T cells secrete IFN‐γ and TNF‐α to promote inflammation, but others produce TGF‐β and FasL to facilitate tumour evasion." (PMID 28224733, 2017). "These tumour-infiltrating T-cell populations are mostly comprised of CD8+ cytotoxic T cells and CD4+ helper T cells (CD4+ Teff and Treg)." (PMID 28447602, 2017). "Previously, we have shown that ACT using a combination of CD4+ Th1 cells and CD8+ CTLs induce superior tumour regression than either subset alone." (PMID 29114389, 2017). "The PBMC to tumor ratio was 20:1 in the cytotoxicity assay; however, since CD8+ plus CD4+ T cells are only 11.15% of the PBMC, the actual T cell to tumor cell ratio was 2.3:1." (PMID 28938530, 2017). "It is also tacitly assumed that the densities of immature dendritic cells and naive CD4+ and CD8+ T cells are constant throughout the tumor tissue." (PMID 28542574, 2017). "For an efficient DC-based cancer vaccine, generated mDC have to be able to home to lymphoid tissue and, once there, efficiently stimulate tumor-specific Th1-type CD4+ T cells and CD8+ CTL that are able to eliminate tumor cells." (PMID 28601925, 2017). "In contrast to CD4+Teffs, the proportion and the frequency of Treg clones sharing the same TCR were very different not only among tumor infiltrates, where the differences were most pronounced but also in dLN and pLN." (PMID 28638937, 2017). "With tumor TNM stage advanced, less CD4+, CD8+ and Foxp3+ cell infiltration and PD-1 expression was found in the complete cohort." (PMID 28978018, 2017). "CD4+ and CD8+ T cells elicited in response to microbial invasion or tumor growth are subject to immune control to avert undue immunopathology and autoimmunity." (PMID 29033936, 2017). "In our case, a significant lymphocytic aggregation comprising CD3+CD4+ T cells and CD20+ B cells was observed around the tumor in the biopsy specimen." (PMID 28488173, 2017). "Tumor-infiltrating T cells, such as CD3+, CD4+, and CD8+ T cells were determined by immunohistochemistry." (PMID 29163521, 2017). "Decrease in CD4 count while on PLD has been described, this fact needs further research to understand the role of PLD in the development of secondary neoplasia and its ultimate benefit in Kaposi’s therapy." (PMID 28558783, 2017). "The intra-tumoral CD8+, CD4+, and CD45RO+ lymphocytic cellular infiltrates displayed upward trends over time for each tumor subtype with the exception of samples obtained at autopsy." (PMID 29137242, 2017).
tumor (continued). "In cancer patients, Tregs are induced by tumour or stroma-secreted factors and also regulated by effector B, T cells, and OX40/OX40L expressed on activated CD4+ and CD8+ T cells, members of the TNFR/TNF superfamily." (PMID 28572863, 2017). "The present data indicated that all immune cells including T cells (CD3+CD4+, CD3+CD8+), B cells, and NK cells were involved in rejection of the RAMOS tumor." (PMID 28399128, 2017). "Efficient immune response requires activation of CD4 and CD8 T lymphocytes and activation of tumor-infiltrating cytotoxic T lymphocytes is correlated with improved survival in cervical, endometrial, ovarian, pancreatic and colorectal cancers." (PMID 28659181, 2017). "The percentage of PD-L1+ cells in CD4+ and CD8+ TIL was positively correlated with tumor size, IHC scores for %stromal TIL, %global TIL, %intratumoral TIL, and %CD8+, even if only a low proportion of PD-L1+ TIL was detected." (PMID 29163490, 2017). "When animals that had rejected the initial tumor and the first rechallenge with GL261/ErbB2 were injected once again with GL261/ErbB2 cells but this time after depletion of CD4+ and CD8+ T cells, tumors formed in a large proportion of the mice." (PMID 28572802, 2017). "VEGFR2, one of its two key receptors, is selectively expressed by Foxp3high CD4+ Tregs and VEGF-A has been shown to induce Treg proliferation in a VEGFR2-dependent manner in tumor-bearing mice and metastatic colorectal cancer patients." (PMID 28348554, 2017). "Myeloid cell specific deletion of TRAF-2 resulted in less tumor growth and lower TAM infiltration along with higher intratumoral IFN-γ produced by higher percentage of CD4+ and CD8+ T-cell infiltration." (PMID 28197019, 2017). "Previous work on α-Lactalbumin vaccination has shown amplification of and involvement of both CD4+ and CD8+ cells in the anti-tumor immune response post α-Lactalbumin targeted vaccination." (PMID 28430646, 2017). "Tumor-infiltrating leukocytes were identified using CD45 antibody, and staining with CD3, CD4, and CD8 antibodies was used to identify T lymphocyte subsets." (PMID 28603527, 2017). "This vaccine produced a reduction of tumor growth in vitro and the immunological response was T CD8+ dependent and T CD4+-independent, suggesting that HPV16 E5 is an antigen able to induce tumor rejection." (PMID 28545552, 2017). "This appears to result in the immune activation in the periphery, secondary lymphoid organs, and massive infiltration of CD4+, CD8+, and NK cells in the tumor, which correlates well with the tumor control." (PMID 28447025, 2017). "PD-1 and LAG-3 are co-expressed on dysfunctional or exhausted virus-specific CD8+ T cells, and on both CD4+ and CD8+ tumor infiltrating lymphocytes (TILs) in animal models of cancer." (PMID 28545567, 2017). "Of the two MPNST samples obtained at the same time from within the same tumor 12 years after original diagnosis, the low-grade sample exhibited much higher CD8+, CD4+, FOXP3+, CD45RO+, and CD56+ lymphocytic infiltrates than did the high-grade MPNST sample." (PMID 29137242, 2017). "Taken together, tumour antigen-specific CD8+ iTSCM cells are more likely to have potent antitumour effects, and the combination with the CD4+ iTSCM cells and the CD8+ iTSCM cells are thought to provide the strongest antitumour effects." (PMID 28530241, 2017). "Recently, a study shows that the inhibition of DPP4 will increase CD4+ and CD8+ T lymphocytes and delayed tumor growth." (PMID 27936466, 2017). "Treg cells infiltrate tumors and inhibit antitumor immune responses by tumor antigen-specific CD8 T cells and CD4 T cells." (PMID 29463952, 2017). "The authors describe the suppression of tumor formation in mice vaccinated with DC fused with HCC cells and demonstrate that protection was mediated by the CD4+ T cells elicited, since it was completely abrogated by anti-CD4 antibodies." (PMID 28289418, 2017).
tumor (continued). "In order to explore which effecter cells involved the antitumor effect of BAFF-E7 DNA vaccine, neutralizing antibodies target CD4, CD8, and NK 1.1 were administered to BAFF-E7 vaccinated and TC-1 tumor-bearing mice." (PMID 28423693, 2017). "It is well recognized that cytotoxic CD4+, CD8+ and Foxp3+ TIL constitute the most important effector mechanisms of anti-tumour immunity." (PMID 28322245, 2017). "Here we compared primary CD4+ and CD8+ T cells expressing wild‐type and a range of affinity‐enhanced TCRs specific for the HLA A*0201‐restricted NY‐ESO‐1‐ and gp100 tumour antigens." (PMID 27324616, 2017). "FACS analysis revealed an increased frequency of IFN-γ-positive CD4+ and CD8+ effector T cells both in the draining lymph node (dLN) and the spleen of tumor-bearing FAM73b KO mice." (PMID 29180626, 2017). "Early research showed that a high degree of CD8+ and CD4+ T-cell infiltration in ESCC correlated with favorable clinical outcome, suggesting that the tumor antigen-specific cellular immune response plays a role in the clinical disease course." (PMID 28404915, 2017). "One of the most important features of the combination therapy was its ability to enhance both CD4+ and CD8+ T-cell responses against the tumor antigen Twist in the lung, which likely resulted from increased T-cell priming at the vaccine DLN." (PMID 29207606, 2017). "To assess the effects of oncolytic Ads on the CD4+CD25+Foxp3+ Treg cell population, we examined draining lymph nodes (DLNs) from tumor-bearing mice by fluorescence-activated cell sorting (FACS)." (PMID 28002796, 2017). "Histology studies of regressing tumors at 1 week after therapy, revealed extensive tumor destruction and a heavy infiltration of CD45+ leukocytes including F4/80+ macrophages, CD8+ cytotoxic T cells and CD4+ helper T cells." (PMID 28116088, 2017). "The in vivo relevance of CD4+ CTL in the different phases of infection and in tumor development is rarely directly demonstrated and can be principally inferred from in vitro experiments as well as from clinical results of immunotherapeutic interventions." (PMID 28289418, 2017). "In tumor sections, treatment with IMQ combined with IR increased the infiltration of CD4+ and CD8+ T cells in tumor tissues." (PMID 28212561, 2017). "Tumor-infiltrated CD4+Foxp3+ Tregs highly express CD25, while CD4+Foxp3- cells did not, allowing the anti-CD25-Ce6 complex to specifically target tumor-infiltrated Tregs." (PMID 28537894, 2017). "Tumor infiltration of CD3+, CD4+, and CD8+ cells was observed after the injection of InCVAX, which indicated the in situ elimination of the tumor." (PMID 28218682, 2017). "DCs take up tumour antigens, transport them to the lymph nodes, presenting via MHC Class I and II to CD8+ and CD4+ T cells and induce a tumour-specific immune response." (PMID 27743144, 2017). "Since digital quantification of TILs can solve this problem, we first established the pipeline of counting CD45+, CD4+, CD8+ and CD68+ TILs inside and outside tumor areas that were manually outlined." (PMID 28923066, 2017). "Intranasal delivery of CCL2 to BALB/c mice markedly enhanced seeding and outgrowth of 67NR cells in the lung and increased the recruitment of CD4+ T cells and CD8+ central memory T cells into lungs of tumor bearing mice." (PMID 28143493, 2017). "Co-transferring CD4+ Th1 cells and CD8+ CTLs has been observed to induce a synergistic antitumour response, resulting in complete regression in 80% of the tumour-bearing mice." (PMID 29114389, 2017). "We performed tumor growth studies using IR + anti-CCR2 treatment while depleting CD8+ and CD4+ T cells." (PMID 29170400, 2017). "On activation, CD8 cytotoxic T cells (CTLs) eliminate tumour cells directly by the production of IFN-Gama, whereas CD4 T helper cells stimulate B cells supporting cytotoxic and humoral immune response." (PMID 28275390, 2017).
tumor (continued). "We found both factors had an upwards trend upon recurrence; we next separated tumor-infiltrating T cells into perivascular and intratumoral CD3+, CD4+, CD8+, and Foxp3+ T cell subsets." (PMID 29163521, 2017). "Addition to clinical effects, the immunologic effects were increased including proliferation of circulation CD4+ and CD8+ T-cells, responses to recall and naive reporter antigens, and endogenous tumor-specific immune responses." (PMID 28085094, 2017). "The combined use of anti-PD-1 with an anti-CD4 mAb mediated a very potent, CD8-dependent, synergistic effect leading to significant elongation of tumor-free survival of mice, complete tumor regression and durable anti-NB immunity." (PMID 29070883, 2017). "Tumor cells and PBMCs co-cultured or cultured individually were evaluated by flow cytometry with a multiparameter panel to assess CD45, CD3, CD4, CD8 and Foxp3 expression." (PMID 29371976, 2017). "Enumeration of CD4+, CD8+ and CD3+ T cells in the tumor microenvironment confirmed an increase in CD8+ and CD3+ T cells in CEA.Tg mice treated with the vaccine and mGITRL-FP." (PMID 29088720, 2017). "We found that the tumor cell produced IDO and/or galectin-3, and the accumulation of CD4+CD25hiFoxP3+ T cells suppressed the expansion of tumor-specific T cells in the MLTC." (PMID 28401257, 2017). "The varying extent of enrichment of p16Ink4a-positive and -negative tumors in the number of CD8+ and CD4+ cells may be a consequence of diverse expression of tumor associated antigens (TAAs), MHC antigens, costimulatory molecules, and the statuses of antigen-presenting cells (APCs)." (PMID 28515351, 2017). "Thus, Nutlin‐3a may suppress tumor growth by potentiating the function of CD4+T cells." (PMID 28544818, 2017). "Studies have shown that patients of breast cancer have lower absolute numbers of peripheral blood lymphocytes but increased numbers of functionally suppressive CD4+CD25+ regulatory T cells (Tregs) in the peripheral blood and tumor microenvironment." (PMID 28099147, 2017). "Immune checkpoint molecule PD-1 is expressed by various immune cells, including tumor-infiltrating CD8(+) T cells and CD4(+) T cells, and is activated by its ligands (either PD-L1 or PD-L2)." (PMID 28754154, 2017). "The percentage of CD4+ T cells present in the effusions is significantly correlated with response to chemotherapy, while the percentage of PD-L1+ PDPN+ tumor cells can be translated as a significant prognostic factor for worse outcome." (PMID 29163783, 2017). "In line with the Th1 profile of the immune response, Nm-fHbp-vIII-OMVs immunization promoted a significant increase of CD4+ and CD8+ T cells at tumor site and a concomitant reduction of both CD4+ Treg and MDSC cells." (PMID 29164053, 2017). "With the help of CD4+ T-cells, CD8+ T-cells can control tumor growth by their cytotoxic activity and the induction of apoptosis in tumor cells." (PMID 28489884, 2017). "Consistent with the expression of α-SMA in the tumor samples, CD4+ T cells were predominantly found in the stroma of Fuhrman III–IV compared with Fuhrman I samples and the expression of CD4 was positively correlated with α-SMA expression in patients." (PMID 28846080, 2017). "Detectable expression levels of CD137 on blood and tumor CD8+ T lymphocytes (and to a lesser extent in CD4+ T cells) at diagnosis were correlated to response to combined anti-PD-1/CTLA-4 mAbs." (PMID 28928380, 2017). "In contrast, significant increases in proliferating CD4+ T-cells and Tregs (as a % of CD45+ cells) vs. control group, were observed in the tumor." (PMID 28807001, 2017). "The therapeutic effect of the combination therapy was dependent on tumor infiltration by CD8+ and CD4+ T cells, NK cells, and levels of type I interferon, and it was less dependent on the sensitivity of the cancer cells to NDV-mediated lysis." (PMID 28536354, 2017).